RNU6-1218P (RNA, U6 small nuclear 1218, pseudogene)
Gene: Small nuclear RNA gene on chromosome 8 (30,043,801 to 30,043,908, reverse strand). Ensembl gene ENSG00000239175.
Homologues: Orthologues: chimpanzee U6 (98% identical), macaque U6 (87% identical), dog U6 (73% identical), rat U6 (72% identical), mouse Gm23199 (68% identical). Paralogues in human: RNU6-1083P (84% identical), RNU6-1152P (82% identical), RNU6-16P (82% identical), RNU6-348P (82% identical), RNU6-797P (82% identical), RNU6-1047P (81% identical), RNU6-1181P (81% identical), RNU6-35P (81% identical), RNU6-393P (81% identical), RNU6-41P (81% identical), RNU6-44P (81% identical), RNU6-968P (81% identical), and 1288 more.